MGLL (monoglyceride lipase)
Diseases named in the same sentence as MGLL in open-access papers (continued):
Sharing a sentence is not in itself a finding about the gene and the disease.
diffuse large B-cell lymphoma (2 papers, 2023 to 2025). "Interestingly, MGLL gene expression was highly positively related to M1-type macrophages in acute lymphoblastic leukemia (ALL, R = 0.58) and lymphoid neoplasm diffuse large B-cell lymphoma (DLBC, R =0.60) and considerably positively associated with M2-type macrophages in UM (R = 0.60)." (PMID 37033945, 2023).
endometritis (2 papers, 2022 to 2024). An acute or chronic, usually bacterial infectious process affecting the endometrium. "MGLL expression was significantly upregulated in cows with endometritis at 7 weeks postpartum, while NAAA expression was consistently downregulated in cows with fatty liver." (PMID 39273135, 2024). "MGLL expression demonstrated the most significant change among all genes studied in relation to endometritis." (PMID 39273135, 2024). "The significant upregulation of MGLL in cows with endometritis at 7 weeks postpartum is a critical finding with potential implications for the persistence of endometrial inflammation." (PMID 39273135, 2024). "It was previously reported that MGLL gene expression decreased in AT of PP cows experiencing higher inflammation and lipolysis, which is in accordance with reduced MGLL expression in cows suffering from endometritis." (PMID 35327191, 2022). "Cows with endometritis at 7 weeks postpartum showed a marked increase in MGLL expression." (PMID 39273135, 2024). "The observed patterns of gene expression, particularly the upregulation of MGLL in endometritis and the downregulation of NAAA in fatty liver, suggest that the ECS may play a crucial role in modulating inflammatory responses and lipid metabolism in the postpartum uterus." (PMID 39273135, 2024).
liver disease (2 papers, 2023 to 2025). "Extensive research has indicated that MGLL plays a critical role in maintaining metabolic homeostasis, with its dysregulation linked to the pathogenesis of several liver diseases." (PMID 40245985, 2025). "As a result, MGLL has emerged as a promising therapeutic target for liver diseases, with recent studies highlighting its potential in NAFLD and NASH." (PMID 40245985, 2025). "Moreover, the identification of MGLL as a key target for AKBA further strengthens the rationale for developing MGLL inhibitors as a therapeutic strategy for liver diseases." (PMID 40245985, 2025).
ovarian serous cystadenocarcinoma (2 papers, 2023 to 2025). A malignant serous cystic epithelial neoplasm arising from the ovary. "Further cox regression analysis of 38 tumors indicated that MGLL expression significantly correlated with PFS in 5 cancers and was a risk factor for UM (p = 6.0e-7), PAAD (p = 1.7e-3), STAD (p = 4.0e-3), and ACC (p = 0.03), but a protective factor for ovarian serous cystadenocarcinoma (OV, p=0.03)." (PMID 37033945, 2023).
alcoholism (1 paper, 2021). "The GMDR analysis suggests that a certain combination of SNPs along the CNR1-DAGLA-MGLL genes protect against or pose a risk for alcoholism, by presumably modulating DAGLA and or MGLL expression and subsequently 2-AG levels." (PMID 33959052, 2021).
anorexia nervosa (1 paper, 2008). A disorder most often seen in adolescent females characterized by a refusal to maintain a minimally normal body weight, an intense fear of gaining weight, a disturbance in body image, and, in postmenarcheal females, the development of amenorrhea. "The aim of this study was to analyse whether nucleotide sequence variations in the CNR1, FAAH, NAAA and MGLL genes are associated with anorexia nervosa (AN)." (PMID 19014633, 2008).
bladder cancer (1 paper, 2020). "To better understand the role of ECs and NAEs in bladder cancer, we analyzed gene expression data from TGCA database regarding the metabolic pathway of the ECS, comprising the synthetic enzymes (PLCB1-4, PTPN22, ABHD4, GDE1, DAGLA, DAGLB, and NAPE-PLD) and the hydrolytic ones (FAAH, NAAA, and MGLL)." (PMID 32260109, 2020).
endothelial dysfunction (1 paper, 2025). In vascular diseases, endothelial dysfunction is a systemic pathological state of the endothelium (the inner lining of blood vessels) and can be broadly defined as an imbalance between vasodilating and vasoconstricting substances produced by (or acting on) the endothelium. "This study identifies MGLL as a key regulator of PA accumulation and endothelial dysfunction, offering a promising therapeutic target for vascular aging." (PMID 40972970, 2025). "By inhibiting MGLL-mediated PA accumulation, TZ alleviates endothelial dysfunction and vascular aging." (PMID 40972970, 2025).
testicular germ cell tumor (1 paper, 2023). A germ cell tumor arising from the testis. "Using TIMER2, we examined the connection between pan-cancer macrophage infiltration and MGLL expression and found a positive correlation between them in DLBC, testicular germ cell tumor (TGCT), thymoma (THYM), and UM." (PMID 37033945, 2023).
type 1 diabetes (1 paper, 2024). "Beta cells from type 1 diabetes donors had higher MGLL expression levels (encoding the endocannabinoid enzyme MAGL) than those from healthy donors." (PMID 38864887, 2024).
vitiligo (1 paper, 2025). Generalized well circumscribed patches of leukoderma that are generally distributed over symmetric body locations and is due to autoimmune destruction of melanocytes. "In conclusion, PTGDS, PNPLA8, and MGLL were implicated in AAM to influence the pathogenesis of vitiligo." (PMID 40078960, 2025). "The RT-PCR results showed that compared with the control group, the expressions of PTGDS and MGLL in the skin tissues of vitiligo patients were significantly downregulated, whereas the expression of PNPLA8 was significantly upregulated." (PMID 40078960, 2025). "Therefore, MGLL may participate in the immune response process of vitiligo by regulating the activation and functions of immune cells." (PMID 40078960, 2025). "In this study, we first obtained six AAM-RGs in vitiligo by searching the transcriptome dataset in the GEO database along with difference analysis and machine learning; then, PTGDS, PNPLA8, and MGLL were verified as the three key genes through the validation set." (PMID 40078960, 2025). "However, the specific roles of MGLL and PNPLA8 in vitiligo are not directly reported; thus, future studies may further explore the roles of these enzymes in vitiligo and their potential clinical applications." (PMID 40078960, 2025).
cancer (130 papers, 2012 to 2026). A tumor composed of atypical neoplastic, often pleomorphic cells that invade other tissues. "We specifically focus on MGLL’s association with clinical outcomes, protein interactions, immune cell infiltration, and m7G methylation, as these factors are implicated in cancer biology and may influence therapeutic responses." (PMID 40994935, 2025). "MGLL has been implicated to play a pathophysiological role in various cancers." (PMID 37033945, 2023). "It is well-known that EAC is a malignant tumor associated with abnormal lipid metabolism, and MGLL may play an important role in it, our group found that MGLL was overexpressed in progesterone resistance cells compared to sensitivity cells in previous studies." (PMID 36550099, 2022). "Furthermore, MGLL was associated with lipid metabolism which plays a critical role in malignancy of cancer cells and indeed, lipid metabolism was affected by CDV in HeLa and HaCaT cells." (PMID 23702334, 2013). "Importantly, the loss-of-function of monoglyceride lipase was partly rescued by exogenous palmitate supplementation, thereby demonstrating that the fatty acids liberated by MG hydrolysis are essential mediators of cancer cell migration." (PMID 33413672, 2021). "Pan-cancer analysis revealed significant expression variations of MGLL across multiple tumor types, suggesting its potential involvement in core regulatory mechanisms of common oncogenic pathways." (PMID 40994935, 2025). "To explore the significance of MGLL in tumor tissues, we first analyzed its expression in pan-cancer tissues." (PMID 40994935, 2025). "MGLL expression was higher in cancer cells with the transcriptional program termed glandular, which was enriched in PNI foci." (PMID 40075699, 2025). "MGLL exhibits dual roles in cancer, acting as either a tumor suppressor or an oncogenic factor, depending on the cancer type." (PMID 41345744, 2025). "MGLL inhibitors have been considered important agents in many diseases for their anti-nociceptive, anxiolytic, anti-inflammatory, and anti-cancer properties." (PMID 38612674, 2024). "We then examined MGLL expression in cancer cells and macrophage makeup invading them and found that MGLL expression on cancer cells was positively correlated with SPP1-ACP5 macrophage infiltration." (PMID 37033945, 2023). "Since this work indicated a relationship between MGLL expression and immune cell infiltration in various malignancies, we explored immune cell infiltration in pan-cancers." (PMID 37033945, 2023). "We also discovered that cancer cells had elevated levels of MGLL expression, which switched macrophages to the pro-tumor M2 phenotype." (PMID 37033945, 2023). "Interactions between TAMs and cancer cells are known to be regulated by monoacylglycerol lipase (MGLL), a key enzyme involved in the metabolism of triacylglycerol." (PMID 37205182, 2023). "Another cancer‐related gene involved in lipid metabolism and macrophage activation is monoacylglycerol lipase (MGLL) contributing to lipid accumulation in macrophages and regulating tumor progression." (PMID 38037545, 2023). "On the other hand, overexpression of MGLL by cancer cells can promote the generation of free FAs, which are an important nutrient source for tumors." (PMID 37205182, 2023). "One such lipase, monoacylglycerol lipase (MAGL or MGLL), is upregulated in aggressive cancers, wherein its suppression impedes tumor growth and metastasis." (PMID 35732120, 2022). "Meanwhile, macrophages derived from a transgenic mouse model exhibiting MGLL overexpression were shown to accumulate lipids, and such macrophages preferentially polarized into the M1 phenotype in response to cancer-specific stimuli." (PMID 36131916, 2022). "Meanwhile, MΦs, derived from a transgenic mouse model with a specific overexpression of MGLL (TgMGLL) in myeloid cells, were refractory to accumulated lipids in response to cancer cell stimuli." (PMID 34476174, 2021).
cancer (continued). "Studies have revealed that MGLL is highly expressed in a number of aggressive human cancer cells and primary tumors, and overexpression of MGLL promotes tumor migration, invasion, and proliferation." (PMID 33363004, 2020). "MGLL can promote cancer cell proliferation in many ways, such as via fatty acid accumulation, regulation of the cell cycle, and inhibition of apoptosis." (PMID 33363004, 2020). "We therefore evaluated the role of MGLL in cell proliferation in A549 and H322 cells and found that MGLL knockdown inhibits cancer cell proliferation both in vitro and in vivo." (PMID 33363004, 2020). "MGLL (Monoglyceride lipase) is highly expressed in aggressive human cancer cells and primary tumors, where it regulates a fatty acid network enriched in oncogenic signaling lipids that promotes migration, invasion, survival, and in-vivo tumor growth." (PMID 32998690, 2020). "It is interesting that the expression of MGLL in TAMs and cancer cells was contradictory, although those two types of cells were in the same microenvironment." (PMID 29968710, 2018). "Deregulations of miR-21 and miR-130b, as well as deregulation of GPD1L, HLF, HPGD and MGLL have been reported either in HNOC or other cancer types, and these MRMs represent significant functional relevance in OTSCC." (PMID 27561985, 2016). "The current knowledge regarding the regulation and biological functions of MGLL in neoplastic diseases remains limited, with the exact role of MGLL in various aspects of cancer biological processes being rarely characterized." (PMID 27366945, 2016). "MGLL, a monoglyceride lipase overexpressed in several cancers, was significantly downregulated in recurrent EBV reactivated cells and in all 31 NPC biopsies." (PMID 23024765, 2012). "In this pathway, MGLL catalyzes the hydrolysis of 2-arachidonoylglycerol (2-AG), an antagonist of the endocannabinoid system, which plays a crucial role in pathophysiological processes such as cancer proliferation, inflammation, pain and neuroprotection." (PMID 40075699, 2025). "Interestingly, MGLL in cancer cells promoted tumor progression by releasing special fatty acids whereas MGLL in TAMs suppressed cancer development by attenuating endogenous cannabinoid receptor 2 signaling." (PMID 37033945, 2023). "Therefore, MGLL affects immune cell infiltration especially macrophage polarization in various cancers." (PMID 37033945, 2023). "Despite the MG pool being small relative to TG, DG, and glycerophospholipids levels, monoglyceride lipase exerts significant influence on cancer cell behavior, and MG hydrolysis enzyme activity is more than 11-fold higher in cancerous lung tissues than in paired non-cancerous tissues." (PMID 33413672, 2021). "Of these, CAT represents catalase, a key antioxidant enzyme which has been implicated in resistance to antileukemic agents such as doxorubicin, and MGLL (also known as MAGL) represents monoglyceride lipase, which has been shown to be overexpressed in aggressive cancers." (PMID 34202615, 2021). "Previous studies have also reported that MGLL is involved in endocannabinoid signaling, and notably, the endocannabinoid system has been found to play a significant role in cancer development and may serve as a therapeutic target." (PMID 33363004, 2020). "Critically, MGLL has also been found to contribute to tumorigenesis and cancer metastasis." (PMID 33363004, 2020). "In the present study, we screened lipid metabolism-related genes in TAMs and found that deficiency of monoacylglycerol lipase (MGLL) contributed to lipid accumulation, macrophage activation, CD8+ T cell inhibition and tumor progression in inoculated and genetic cancer models." (PMID 29968710, 2018). "Hormone sensitive lipase (HSL) converts monoacylglycerides to free fatty acids and glycerol (MGLL or MAGL) (k159) and this step regulates the quantity of fatty acids, which are used as signaling molecules and have been shown to promote cancer cell migration, invasion and tumor growth." (PMID 29706895, 2018).
cancer (continued). "MGLL may also play a role in certain types of cancer by regulating both endocannabinoid and fatty acid pathways, and supporting protumorigenic metabolism." (PMID 27561985, 2016). "These contentions on the functional role of MGLL suggest that its complex disparity in cancer biology may be tumor context-dependent." (PMID 27366945, 2016). "However, we observed a high heterogeneity in MGLL immunoreactivity in cancer cells in the TME." (PMID 40075699, 2025). "Monoacylglycerol lipase (MGLL) deficiency, in particular, induces lipid accumulation in TAMs, enhances CB2/TLR4-dependent macrophage activation, and subsequently hinders the function of CD8+T cells associated with tumors and impedes the development of various cancers." (PMID 38185636, 2024). "Besides, MGLL expression and immune infiltration were correlated in 43 cancer types." (PMID 37033945, 2023). "A few cancers or cancer-related genes [such as EPHA1 (OMIM*179610), MGLL (OMIM*609699), DLG1 (OMIM*601014), SLC49A4 (OMIM *602773)] have also been observed." (PMID 38540211, 2024). "In addition, we discovered that MGLL is strongly expressed in macrophages, specifically M2 macrophages, which may play a function in the M2 polarization of macrophages and M2 macrophage activation in cancer cells." (PMID 37033945, 2023). "CAY10499, an inhibitor of HSL/MGLL, has been reported to suppress PDAC cell invasion by reducing the availability of fatty acids that would otherwise fuel cancer metastasis." (PMID 37978383, 2023). "Hence, targeting MGLL could be exploited for the treatment of cancer." (PMID 36131916, 2022). "Taken together, our findings identify MGLL as a switch for CB2/TLR4-dependent macrophage activation and provide potential targets for cancer therapy." (PMID 29968710, 2018). "Collectively, we demonstrated that MGLL functioned as a CB2-dependent switch in regulating the activation of TAMs, exhaustion of CD8+ T cells and subsequent development of cancers." (PMID 29968710, 2018). "Our results showed that MGLL gene and protein expression levels are higher in the cancer compartment within PNI compared to non-PNI regions." (PMID 40075699, 2025). "Both in vitro cancer-stimulated macrophages and TAMs isolated from different tumor models exhibit an increased expression of ABHD5, a lipolytic factor of triglycerides, whereas monoacylglycerol lipase (MGLL) is downregulated." (PMID 34476174, 2021). "Of note, HAAO, MGLL, and UPGE were down-regulated in 18 cancer types; ADHFE1, CAT, and MSRA were down-regulated in 19; and RGN was down-regulated in 21 different types of cancer." (PMID 31351478, 2019). "By contrast, the reduced expression or even absence of MGLL has been reported in various common carcinomas, with MGLL proposed as a potential tumor suppressor because of its growth-suppressive effect on cell colony formation." (PMID 27366945, 2016). "Public data showed that MGLL expression was higher in PDAC compared to the normal pancreas, and our data suggested that MGLL gene expression and immunoreactivity were higher in PNI foci, potentially indicating that cancer cells are more proliferative and invasive in these regions." (PMID 40075699, 2025). "We hypothesize that the up-regulation of MGLL leads to the hydrolysis of 2-AG increasing lipid signaling, which may play a role in PDAC growth, migration and invasion potential and may contribute to cancer pain." (PMID 40075699, 2025). "Therefore, it is not wise to interrupt cancer progression by simply modulating the expression or activity of MGLL because MGLL-related drugs are not specific to macrophages or cancer cells." (PMID 29968710, 2018). "We first used IHC staining to detect MGLL expression in 156 LUAD samples and 76 adjacent non-tumor tissues and found that MGLL expression is significantly overexpressed in cancer tissues relative to non-tumor tissues." (PMID 33363004, 2020).